AHR (aryl hydrocarbon receptor)
Diseases named in the same sentence as AHR in open-access papers (continued):
Sharing a sentence is not in itself a finding about the gene and the disease.
tumor (continued). "Whereas IDO1 has largely been studied in the context of Trp-IDO1-Kyn-AhR signaling, IDO1 may also promote tumor progression through non-enzymatic functions." (PMID 37876966, 2023). "Finally, we provide evidence of this antagonistic relationship in ccRCC tumours, which display an overall negative correlation between HIF- and AHR-target gene expression." (PMID 36725335, 2023). "Inhibitors of the IDO1-Kyn-AhR pathway could abolish the negative effects of CAI on CD8+ T cells and result in complementary and beneficial anti-tumor immune effects." (PMID 31511064, 2019). "In the tumor microenvironment, an increase in kyn concentration may lead to a more substantial rise in KYNA, which has a higher affinity and stability than Kyn, and its resulting AhR activation effect should not be overlooked." (PMID 40103267, 2025). "To address whether dietary AhR agonists modulate the efficacy of checkpoint blockade therapy, we used fibrosarcoma tumor cells expressing the model antigen Ovalbumin (MCA101-OVA), and assessed tumor growth in mice treated or not with anti-PD1." (PMID 41331250, 2025).
cancer (692 papers, 2006 to 2026). A tumor composed of atypical neoplastic, often pleomorphic cells that invade other tissues. "Across multiple cancer models, microbial indole derivatives act as ligands for AHR, driving either protective or pathogenic outcomes depending on the nature of the ligand and the cellular context." (PMID 41540003, 2026). "Further research is needed to fully elucidate the molecular mechanisms underlying TOX's role in cancer, its interactions with AHR, and its potential as a therapeutic target in As3+-related carcinogenesis and other malignancies." (PMID 40303305, 2025). "Tumor metabolic disorder is elevated in HCC and activates the aryl hydrocarbon receptor (AHR), a transcription factor implicated in cancer progression." (PMID 40248203, 2025). "Despite the absence of any significant AhR mutations in any cancer, high AhR activity in cancer is common because of the increased production of endogenous ligands and recruitment of exogenous ligands." (PMID 40650089, 2025). "Aligned topography induces drug resistance through pathways like cytochrome P450 metabolism and the aryl hydrocarbon receptor (AhR), which have been linked to unfavorable prognostic outcomes in cancer." (PMID 40686923, 2025). "For example, certain bile acid metabolites can activate the aryl hydrocarbon receptor (AhR), which is involved in the regulation of immune responses and has been implicated in cancer development." (PMID 40110192, 2025). "Specifically, mutations in APC and AhR deletion have been observed in Wnt/β-catenin-driven cancer models 172-175,177-179." (PMID 40765830, 2025). "AhR can cause metabolic modifications in cancer cells via the regulation of glycolysis and lipid metabolism by interacting with different ligands." (PMID 38434684, 2024). "The deletion of the AHR in different cancer types has been associated with alterations in cell proliferation, invasion, and differentiation." (PMID 39336758, 2024). "For more reliable results, exploring the association between AhR activity and specific drug treatments, especially in patients with stage 3 or 4 cancer, would be valuable." (PMID 38680496, 2024). "Our findings indicate benzo(a)pyrene exposure as a high-risk factor for SCLC and poor outcomes in patients, with the underlying mechanism being the activation of cancer stemness of SCLC cells via the AhR/PKA/SOX2 axis." (PMID 38791215, 2024). "The abnormal AHR activity associated with the progression of cancer has indicated the receptor as a potential drug target for therapeutic applications." (PMID 39204085, 2024). "The use of agonists, antagonists, and cell targeted AhR deficiency in animals has shown AhR’s involvement in the pathogenesis of several diseases, including inflammatory disorders, endocrine perturbations, premature aging, and cancer." (PMID 39474416, 2024). "AhR activity is associated with the pathogenesis of various diseases, including inflammatory diseases, neurological disorders and cancer, making it an attractive target for the development of novel prevention and treatment strategies." (PMID 39438693, 2024). "Perturbations of these physiological functions have been shown to be associated with cancer development and progression, which suggests a complex role of AHR in chemical carcinogenesis." (PMID 38982523, 2024). "AhR has not only been found to be constitutively expressed in cancer tissues but its activation has also been strongly linked to CSC progression and renewal." (PMID 38448800, 2024). "This review aims to discuss the role of exposure to environmental pollutants and activation of AhR on microbiome-associated cancer progression and explore the underlying molecular mechanisms involved in cancer development." (PMID 38448800, 2024). "The network affected by the DM CpGs was associated with cancer, organismal injury and abnormalities, cardiovascular disease, with the top canonical pathways involved including aryl hydrocarbon receptor signaling and molecular mechanisms of cancer." (PMID 37605769, 2023).
cancer (continued). "Aside from AhR’s critical role in physiological processes, the AhR has also been implicated in pathological processes such as inflammation and cancer." (PMID 37408267, 2023). "This is supported by Wnt/β-catenin-driven cancer models with mutations of the tumor suppressor APC and the deletion of AhR, and additional mouse cancer models where the loss of AhR activity resulted in enhanced tumorigenesis and elevated Wnt signaling." (PMID 37106727, 2023). "Cancer and inflammatory diseases are associated with dysbiosis- and host-related aberrant Trp metabolism and inactivation of the aryl hydrocarbon receptor (AHR), which is a receptor of several Trp metabolites." (PMID 37394584, 2023). "The interaction of AhR with members of the NF-kB family is an important aspect, as unresolved chronic inflammation is considered to be an important hallmark of cancer." (PMID 37696458, 2023). "AhR not only transcriptionally regulated epigenetic-associated molecules, but also worked with epigenetic-modifying enzymes during cancer progression." (PMID 37830596, 2023). "In ccRCC, activation of AHR increases cancer cell invasion and is associated with poor patient survival." (PMID 36725335, 2023). "The aryl hydrocarbon receptor has been implicated as an important regulatory pathway in multiple cancers including ESCC." (PMID 37064719, 2023). "The AhR regulates complicated transcriptional processes through interactions with cancer-associated signal transduction pathways." (PMID 37241719, 2023). "The kynurenine-AhR axis is dysregulated in a number of cancers and has been associated not only with increased cell proliferation, but also immune evasion, neo-angiogenesis, metastasis, and chemoresistance." (PMID 37696458, 2023). "Low AhR expression levels were also associated with faster cancer progression and reduced survival in lung ADC patients." (PMID 37696458, 2023). "Evidence indicates that indoleacetic acid activates the aryl hydrocarbon receptor (AhR) and positively regulates cytochrome P-450 enzymes, implicated in tumorigenesis and cancer proliferation." (PMID 36295880, 2022). "Kyn-mediated AhR activation also upregulates the expression of genes encoding IL-6 in cancer cells and macrophages, a proinflammatory cytokine." (PMID 35173722, 2022). "AHR deficiency or inadequate AHR activation predisposes to induction of inflammatory disorders and inflammation-associated intestinal malignancy." (PMID 35935130, 2022). "Exposure to BaP plays a role in lung carcinogenesis, including by directly inducing biological effects associated with cancer by binding to cytoplasmic receptors (Aryl hydrocarbon receptor, AhR)." (PMID 35473600, 2022). "The capacity of cancer associated AhR/CYP1B1, P2Y1r and mGluR5 to upregulate the NAS/melatonin ratio is important." (PMID 36613754, 2022). "Using various in vitro and in vivo models, we now show that formate is able to induce invasion of cancer cells potentially by inducing AhR signalling and its associated CSC regulation." (PMID 35437333, 2022). "Similar results were observed in SUM149, Hs578T and MCF-7 cells where the AhR and its agonists were associated with inducing cancer stem cell characteristics." (PMID 36428667, 2022). "One especially has been the subject of numerous studies since 1998, related to curcumin’s suppression of the transformation of the aryl hydrocarbon receptor (encoded by the Ahr gene) in cancer cells." (PMID 34445271, 2021). "In the current study, the aim was to gain more insight regarding the potential mechanisms associating AhR with immune-related factors in 33 human cancers." (PMID 34290693, 2021). "AhR is strictly associated with the pro-survival signals activation in cancer cells, and believed to collaborate with NF-κB to induce the c-Myc expression in mammalian cells." (PMID 34657603, 2021).
cancer (continued). "Collectively, these indolic compounds can activate AhR, and have demonstrated a reduced cancer risk." (PMID 33916690, 2021). "Aberrant AhR expression often leads to functional anomalies, and is the underlying reason for cancer, as evident from the various in vitro and in vivo models of cancer, with noticeable divergences in pro- and anti-tumorigenic profiles." (PMID 34500672, 2021). "We previously discovered that down-regulation of just half of the p23 cellular content is sufficient in causing a lower cellular content of AHR in various cancer and untransformed cell types in vitro." (PMID 32414129, 2020). "Similar to the detrimental effect of UVB, exposure to BaP in mammals causes a variety of cancers as well as neurotoxicity, and loss of AhR prevents BaP- and UVB-induced carcinogenicity in mice." (PMID 33349622, 2020). "Intriguingly, AhR has been proven to be an environmental sensor and a key regulator of T cell differentiation on which cancer immune surveillance is dependent, so it is reasonable to infer that AhR gene is implicated in carcinogenesis." (PMID 33278884, 2020). "Kyn activates the AhR-ARNT associated transcription of IL-6 in human cancer cell lines, provoking autocrine activation of IDO1 via STAT3." (PMID 32957545, 2020). "The results clearly indicate a complex association between the AHR and several critical cancer features, including increased malignant cell invasion, migration, metastasis, CSC formation, and survival." (PMID 33396563, 2020). "The AhR gene is highly polymorphic, and the relationship between multiple AhR polymorphisms and cancer risk has been investigated." (PMID 33278884, 2020). "In summary, this present study is the most comprehensive and latest meta-analysis concerning multiple AhR polymorphisms and cancer risk to date." (PMID 33278884, 2020). "This study was conducted to quantitatively summarize the association between AhR polymorphisms and cancer risk by meta-analysis." (PMID 33278884, 2020). "Further clinical and functional investigation between AhR polymorphisms and cancer susceptibility are needed." (PMID 33278884, 2020). "On the basis of 17 eligible studies, we have conducted this comprehensive meta-analysis to evaluate the relationship between three AhR polymorphisms and cancer susceptibility." (PMID 33278884, 2020). "PAHs present in the OF of PM are disease and cancer causing agents and known ligands of the aryl hydrocarbon receptor (AHR)." (PMID 30143013, 2018). "In this study, we report that AhR is functionally linked with cancer stem-like properties, and it drives tumorigenesis in the occurrence of radioresistance." (PMID 29706625, 2018). "AhR stimulation causes oxidative stress, inflammation, apoptosis and immunosuppression, and is associated with an increased risk of osteoporosis, cancers and metabolic disorders such as diabetes." (PMID 29721498, 2018). "Depending on the cancer type, two types of results are associated with AhR activity and the prognosis." (PMID 29487603, 2018). "Soot and CB induce cancers at the site of exposure and beyond due to DNA mutations, DNA adducts formation, AhR activation, DNA methylation, and altered oncogenes expressions." (PMID 28713383, 2017). "The most dramatic consequences of the decreased AHR expression are an increased risk of cancer and the inability to protect cells against the toxic effects of xenobiotics." (PMID 29262535, 2017). "The AhR-mediated regulation of aromatic hydrocarbons metabolism has been implicated in a variety of cancers affecting different stages of carcinogenesis." (PMID 26881027, 2016). "Studies on human cancer cells have shown that KYN activates the AhR-ARNT associated transcription of IL-6, which induced autocrine activation of IDO1 via STAT3." (PMID 26881062, 2015). "As such, AhR was found to be over-expressed and constitutively active in a variety of cancers and its nuclear expression is frequently associated with bad prognosis and advanced histological grade." (PMID 25669983, 2015).
cancer (continued). "AHR is a ligand activated transcription factor that has previously been implicated as having roles in differentiation and cancer and we show that AHR is active in vHMEC." (PMID 25960784, 2015). "Halogenated biphenyls, known as PCBs, are industrial toxicants associated with the activation of AhR and downstream adverse effects, including cancer." (PMID 25226618, 2014). "The AhR-mediated regulation of metabolism of polycyclic aromatic hydrocarbons (PAH) has been implicated in a variety of cancers." (PMID 24932473, 2014). "Utilizing Human Gene 1.0-ST array, we show that AhR knockdown alters the expression of several genes known to be linked with cancer." (PMID 24932473, 2014). "We demonstrate that AhR knockdown alters the expression of several genes known to be linked to cancer." (PMID 24932473, 2014). "The effect of shCalpain-10 in cancer cells was associated with inactivation of AhR/Snail promoter binding activity." (PMID 25226618, 2014). "Data from our laboratory and other groups suggest that the sensitivity of cancer cells to AF is associated with cytoplasmic expression of AhR." (PMID 24058584, 2013). "Another concern about using this drug in combination cancer therapy is that like other ligands of the AHR, it does induce cytochrome P450 enzymes, which can cause its own metabolism as well as that of other coadministered pharmaceuticals." (PMID 22970246, 2012). "Furthermore, beyond PMOP, dysregulation of IPA and microbiota-derived indole–AhR signaling has been linked to other chronic disorders affecting bone and systemic metabolism, including inflammatory arthritis and cancer cachexia." (PMID 41508814, 2026). "While AHR’s activation has been classically associated with responses to environmental toxins, recent reports have suggested that it also plays a significant role in cancer biology." (PMID 40248203, 2025). "Moreover, Ahr suppressed intestinal tumorigenesis in APCMin/+ mice 170 and high AHR expression was associated with improved patient survival in some cancers, indicating that Ahr can be targeted for the inhibition of cancer cell proliferation 171-175." (PMID 40765830, 2025). "AHR loss, coupled with Wnt/β-catenin signaling activation, was speculated to promote tumorigenesis in cancer models." (PMID 40765830, 2025). "Furthermore, we have studied the impact of two AhR ligands well known for their critical role in cancer development linked to pollution on AhR and AhR-related gene expression." (PMID 39200369, 2024). "Moreover, activation of the Aryl Carbon Receptor (AhR) by hIDO1 inhibitors has been associated with promoting carcinogenic effects in various human cancers, potentially correlating with unfavorable prognosis." (PMID 38653790, 2024). "The potential mechanisms by which DEHP causes cancer may include activation of nuclear receptors and peroxisome proliferator-activated receptor α, interference with estrogen receptor α and aryl hydrocarbon receptor, and induction of oxidative stress." (PMID 38341560, 2024). "Furthermore, activated AhR causes an inflammatory response that interrupts the immune system’s ability to function correctly, contributing to cancer." (PMID 38518996, 2024). "Overexpression of AhR caused suppression of invasive properties of cancer cells." (PMID 37830596, 2023). "Notably, a pantissue AHR signature has highlighted 3-IAld as one of the metabolites downstream of L-amino acid oxidase catabolism of tryptophan, associated with AHR-driven cancer cell motility and immunosuppression." (PMID 37836434, 2023). "Notably, the interaction of AhR with cancer-associated signaling pathways has been studied also by using its ligands." (PMID 37241719, 2023). "Overactivation of AhR is common in cancer and is associated with poor prognosis." (PMID 37041200, 2023). "Consequently, the AhR has been implicated in cancer stemness serving as a sensor and molecular bridge between environmental exposure to PM and PAHs and an increased risk to develop metastases." (PMID 37696458, 2023).